TNF (tumor necrosis factor)
Diseases named in the same sentence as TNF in open-access papers (continued):
Sharing a sentence is not in itself a finding about the gene and the disease.
malaria (continued). "However, monocytes and macrophages do not produce typical inflammatory cytokines such as IL-6, IL-12, and TNFα during the earliest stages of malaria because of phagosomal acidification, whereas dendritic cells can." (PMID 31662766, 2019). "This could be explained by cell necrosis due to high level of parasitaemia with elevation of produced cytokines such as tumor necrosis factor (TNF) that mediate malaria fever." (PMID 30644435, 2019). "TNF-α production in the liver during malaria, which, according to our study, is potentiated by IL-1α, may be directly involved in the death of hepatocytes and the development of necrotic lesions." (PMID 31110285, 2019). "TNF-α is involved in the induction of fever, which may contribute to suppressing malaria parasitaemia." (PMID 33604551, 2019). "The variability in the TNF-α response to endotoxins could mediate differential host responses which contribute to severe malaria when TNF-α levels are high." (PMID 31294001, 2019). "In a study of malaria infection of children in Mali, severe malaria cases, in comparison with matched healthy controls, showed higher levels of IL-6, IL-10, TNF, IL-12(p70), and IL-6 and IL-10 were higher in severe cases in comparison with matched uncomplicated malaria controls." (PMID 31234875, 2019). "Uncomplicated and asymptomatic malaria significantly raise TNF-α concentrations." (PMID 30275421, 2018). "Furthermore, cytokines such as TNFα and IFNγ which are released during malaria infection, suppress hematopoiesis and hence contribute to anemia, another main pathology of malaria." (PMID 29495555, 2018). "Serum TNF concentration correlates with severity of human malaria." (PMID 29866139, 2018). "In ex vivo analysis of cord blood from mothers in an endemic setting who had experienced malaria during pregnancy, the Vγ9Vδ2 T-cells produced significantly more IFNγ and TNFα than those from healthy mothers, as did the peripheral Vγ9Vδ2 T-cells from the mother." (PMID 30538708, 2018). "Both IFN-γ and TNF-α are also involved immune mediation during human malaria." (PMID 28883981, 2017). "Consequently, given the significant correlation between TNFα levels and hypoglycemia in severe malaria and cerebral malaria, it has been suggested that TNFα be used as a potential prognostic indicator for disease severity." (PMID 29216326, 2017). "Given that TNF-α is a pyrogenic cytokine that significantly contributes towards malaria febrile disease, it indicates that inhibition of CD16+ TEMRA γδ T cells may be necessary to limit immunopathogenesis in the host." (PMID 28615061, 2017). "Since the TNF response induced by malaria PAMPs was generally low and variable for both WT and moesin-deficient cells, potential differences in TNF secretion may not be detectable in this experimental setting." (PMID 28560184, 2017). "In addition, several polymorphisms found under the linkage peak, and more precisely, within TNF, LTA and NCR3 genes, were independently associated with subphenotypes of mild malaria such as parasitaemia or mild malaria attack in Burkina Faso." (PMID 29121672, 2017). "We measured Pf-specific IFNγ-, IL10-, and TNFα-producing CD4 T-cell responses by multi-parametric flow cytometry in 265 children aged 6 months to 10 years enrolled in a longitudinal observational cohort in a high malaria transmission site in Uganda." (PMID 29097996, 2017). "It was proposed that the levels of TNF and IL-6 are indicators of malaria severity." (PMID 27515948, 2016). "In addition, both coinfected groups had increased IL-4, IL-5, IL-7, IL-12, IL-15, IL-17, IFN-γ, and IFN-α and decreased TNF-α relative to malaria alone." (PMID 27418744, 2016). "Malaria induces inappropriate or excessive immune responses by inducing proinflammatory cytokines including interleukin (IL)-1β, IL-6, tumor necrosis factor (TNF)-α, interferon (IFN)-γ, and inducible nitric oxide synthase (iNOS)." (PMID 27422638, 2016).
malaria (continued). "Children with an elevated TNF response to Plasmodium infection are more likely to become sicker than their peers with a lower TNF response capacity, so that the former may experience more frequent episodes of malaria." (PMID 26088606, 2015). "Furthermore, TNF was found elevated in both groups of malaria mono-infection and co-infection with dengue whereas IL-13 was detected in higher amounts in the groups of dengue mono-infection and co-infection." (PMID 26271921, 2015). "In this study, we demonstrate that O. volvulus-infected individuals, residing within co-endemic areas of malaria in Ghana, presented increased IL-6, TNF-α and IL-10 production in response to the P. falciparum-derived antigen MSP-1 when compared to uninfected individuals." (PMID 25889652, 2015). "In addition, malaria antigens have been reported to activate macrophages and monocytes to produce various cytokines, such as tumour necrosis factor (TNF)-alpha and interleukin-1 beta." (PMID 25879828, 2015). "Even so, bias may still have occurred in that study if TNF genotypes varied in frequency of delivery in hospital, or in the frequency of care-seeking behaviour and hospital admission for severe malaria." (PMID 26088606, 2015). "Since this is thought to be required for both effective immunity to malaria and for immunopathogenesis we determined whether intermediate monocytes produce TNF in response to IE." (PMID 26149666, 2015). "Placentas from malaria-infected litters (wild-type and C5ar-/-) showed placental inflammation as indicated by increased expression of tumor necrosis factor (TNF), interferon gamma (IFNΥ), intracellular adhesion molecule-1 (ICAM-1) and monocyte chemotactic protein 1 (MCP-1, CCL2) (p < 0.05)." (PMID 26402732, 2015). "DDX39B and TNF are located in the same major histocompatibility complex (MHC) region on chromosome 6, and therefore assessment of the association of these polymorphisms with the outcomes of malaria can be performed using haplotype analysis." (PMID 25038626, 2014). "Furthermore, TNF-α, a critical cytokine in malaria pathogenesis was shown to mediate expression of inflammasome components and pro-IL-1β." (PMID 24453977, 2014). "Nonetheless, ADCY9 rs2230739 may act to upregulate TGFβ transcription, with the heterozygotes providing some selective advantage since the raised TGF-β levels will down-regulate proinflammatory cytokines, such as TNF, and protect against severe malaria." (PMID 24934404, 2014). "When we assessed the effect of co-infections on cytokine responses in the HHCs who had LTBI, we found that malaria and HIV showed reduced cytokine responses across all cytokine families, with statistically significant associations for TNFα, in keeping with their known immune suppressive effects." (PMID 25372043, 2014). "Malaria also triggered the release of TNFα and IFNγ in both infected groups." (PMID 25242870, 2014). "Indeed, high systemic levels of inflammatory mediators such as TNFα, IFNγ, and aldehydes are correlated with severe malaria in humans." (PMID 25242870, 2014). "Furthermore, TNF-836 CC and IFN-γ-1616 TT genotypes were associated with higher serum concentration of TNF and IFN-γ, respectively, and with susceptibility to severe malaria." (PMID 25124540, 2014). "Tumour necrosis factor (TNF) and interferon gamma (IFN-γ), encoded by TNF-836 C/A (rs 1800630) and IFN-γ -1616 C/T (rs2069705) genes, are key immunological mediators that are believed to both play protective and pathological roles in malaria." (PMID 25124540, 2014). "We found that whilst diminished levels of lipid peroxidation-derived aldehydes and TNFα were detected in animals with malaria that had been treated with capsazepine, IFNγ production remained similar to that observed for samples obtained from vehicle-infected mice." (PMID 25242870, 2014).
malaria (continued). "For malaria infected individuals (M and CI) the profile was high levels of IL-1β, IL-6, TNF-α IL-10, and CRP and decreased levels of IL-17A while for malaria negative individuals (IP and UN) the profile was high levels of IL-17A, NO and decreased levels of IL-10 and CRP." (PMID 25309052, 2014). "PGE2 inhibits TNF-α and appears to decrease malaria severity." (PMID 24669217, 2014). "Similarly, inhibition of bone marrow and RBC destruction as a result of high TNF-α was reported in murine malaria." (PMID 24669217, 2014). "High production of TNF in malaria individuals is related to the development of severe malaria." (PMID 24041406, 2013). "Support for this modulatory hypothesis comes from the description that IL-10 and IL-4 can directly down regulate pro-inflammatory cytokines such as IL-6, TNF and IL-1β and prevent severe forms of malaria." (PMID 23433077, 2013). "Subjects with mild or severe non-lethal malaria displayed substantial loss of interactions in the networks and TNF had significant associations more frequently with other parameters." (PMID 23433077, 2013). "The results presented here shows that PvMSP-119 was able to induce a high cellular activation, leading to production of TNF and emphasizes the high immunogenicity of PvMSP-119 in naturally exposed individuals and, therefore, its potential as a malaria vaccine candidate." (PMID 24041406, 2013). "This suggests that rs1800890 may act to upregulate IL10 transcription, with the heterozygotes providing some selective advantage since the raised IL10 levels will down-regulate proinflammatory cytokines such as TNFα and protect against severe malaria." (PMID 24312262, 2013). "In murine models, the outcome of malaria is sensitive to experimental manipulation of multiple host innate response molecules, such as tumor necrosis factor (TNF), interferon-γ, and erythropoietin, suggesting their role in mediating differential infection outcome." (PMID 23696730, 2013). "In conclusion, the results presented here shows that PvMSP-119 was able to induce a high cellular activation leading to production of TNF, emphasizing the high immunogenicity of PvMSP-119 in naturally exposed individuals and therefore its potential as a malaria vaccine candidate." (PMID 24041406, 2013). "In the group of individuals presenting with severe non-lethal malaria, parasitaemia displayed significant positive associations with TNF, sTNF-RI, IFN-γ, IL-10, CXCL9, CXCL10, SOD-1 and HO-1, while negatively correlated with the chemokines IL-8 and CCL2." (PMID 23433077, 2013). "This study consists of 939 subjects genotyped at 166 single nucleotide polymorphisms (SNPs) from genes involved in known malaria resistance (e.g. HBB, G6PD), cytokine production (e.g. TNF, LTA, IL1, 3, 4, 5, 7, 10, and 13), innate immunity (e.g. TLR 4,9) and the 5q31-33 region (117 SNPs)." (PMID 24098393, 2013). "The inflammatory condition of malaria is charcterised by free radical generation, activation of phospholipase activity resulting in generation of eicosanoids such as prostaglandins and other cytokines (TNF, IFN-γ, and IL-1β)." (PMID 23970953, 2013). "Several studies have demonstrated that the imbalance of pro- and anti-inflammatory cytokines is associated with the immuno-pathogenesis of severe malaria anaemia (SMA) and cerebral malaria (CM) with Tumor necrosis factor (TNFα) and interleukin-10 (IL10) critical in this role." (PMID 24312262, 2013). "Moreover, levels of IL-1β and TNF were higher in children compared to malaria-exposed adults during acute infection despite having a trend to lower parasite density than malaria-exposed adults mounting a higher antibody response to infection." (PMID 23437061, 2013). "Increased presence of TNF-α in malaria infected placentas was documented previously." (PMID 26623293, 2012).
malaria (continued). "In a gene-based association study with 18 candidate genes for malaria susceptibility using 33 SNPs as genetic markers, this study demonstrated that IL1B, IL4R, IL12RB1 and TNF genes were associated with susceptibility to P. vivax malaria in a population of Pará state, Brazil." (PMID 23217179, 2012). "We examined the associations between the frequencies of IFNγ-IL2+TNF−, IFNγ-IL2+TNF+, and IFNγ-IL2-TNF+ T cells and T cells expressing at least TNF or at least IL2 on stimulation with CSP and subsequent risk of clinical malaria in the 6 months that followed the measurement." (PMID 23300801, 2012). "Analysis of basal TNF production according to the CD56dim or CD56bright phenotype confirmed that in acute malaria subjects, as well as in severe malaria, the CD56bright population produced significantly higher levels of the cytokine (p < 0.0001) than the CD56dim population." (PMID 22316273, 2012). "The TNF and LTA genes are implicated in the host defense and pathogeneses of severe malaria." (PMID 22615793, 2012). "Analysis of basal IFNγ and TNF levels confirmed the CD56bright NK population as the main cytokine producer (p < 0.0001) in the groups affected with malaria, with the CD56dim NK cell exhibiting the highest potential of TNF production after stimulus in the acute malaria group." (PMID 22316273, 2012). "Furthermore, HBB, IL4, TNF, and FCGR2A have been associated with both malaria resistance and IgG levels." (PMID 22947458, 2012). "However, after 6 hours of stimulus with calcium ionophore, CD56dim cells from acute malaria and from severe malaria subjects produced significantly higher levels of TNF." (PMID 22316273, 2012). "Human monocytes and murine macrophages treated with PPARγ agonists generate significantly less TNF in response to malaria-related inflammatory stimuli including parasite lysates and P. falciparum glycosylphosphatidyl inositol (GPI), a malaria toxin that interacts with TLR2." (PMID 21772838, 2012). "No study has reported the expression of NF-κB in PBMCs from malaria patients and its association with circulating cytokines such as IL-10 and TNF." (PMID 22682094, 2012). "TNF is involved in the immune response to malaria as well as in the pathogenesis of severe disease." (PMID 22316273, 2012). "MIF, together with other proinflammatory factors such as IFN-γ and TNF-α, may then activate these macrophages to clear and kill malaria parasites in the placenta." (PMID 23272137, 2012). "A proximate cue for such a strategy may arise from the production of TNFα by cells of the innate immune system upon binding malaria waste products as well as intracellular debris." (PMID 22718989, 2012). "Monocytes produced high levels of IL-1β, IL-6 and TNF-α during acute malaria." (PMID 22745844, 2012). "In patients with vivax malaria, TNF-a and IFN-g have been associated with malaria anaemia and may be involved in promoting inadequate erythropoiesis." (PMID 22624872, 2012). "In controlled Plasmodium infections of malaria-naïve subjects, serum levels of pro-inflammatory cytokines, including TNF-α, IL-6, IFN-γ, and IL-12p40, increase at the time that parasites emerge from the liver and at the first appearance of parasitized erythrocytes." (PMID 22745697, 2012). "HBB, IL4, IL12, TNF, LTA, NCR3 and FCGR2A polymorphisms have been associated with malaria resistance in humans, whereas cytophilic immunoglobulin G (IgG) antibodies are thought to play a critical role in immune protection against asexual blood stages of the parasite." (PMID 22947458, 2012). "TNFα and IFNγ producing CS-specific CD4+ T cells were at much lower frequencies among control vaccinees, but nevertheless were associated with reduced risks of clinical malaria of borderline significance." (PMID 21998698, 2011). "Moreover, rosiglitazone and IL13 have been shown to promote in vitro an increase in CD36-mediated phagocytosis and a decrease in malaria parasite-induced TNF-α release both on murine macrophage and human monocytes." (PMID 21949655, 2011).
malaria (continued). "During malaria blood stage infection, the production of TNF-α is increased, and these cytokine might modulate new liver stage infections." (PMID 21394207, 2011). "In addition, many observations provide evidence that leukocytes and inflammatory cytokines, such as tumor necrosis factor (TNF), are involved in malaria pathogenesis." (PMID 21603600, 2011). "Indeed, a borderline statistical correlation between TNFα+ CD4+ T cells and a reduced risk of clinical malaria was observed among control vaccinees." (PMID 21998698, 2011). "In addition, proinflammatory cytokine such as TNF-α released against malaria antigens would adversely affect the nutritional status." (PMID 20500831, 2010). "The role of leukocytes in malaria pathogenesis is still not fully understood; nevertheless, it has been shown that these cells are the main source of pro-inflammatory cytokines, especially TNFα which is highly pyrogenic." (PMID 21080932, 2010). "The potential importance of such genes was highlighted in a recent study showing that SNPs in HLA-B associated transcript 2 (BAT2) in the MHC III region were associated with severe malaria susceptibility, while TNF and LTA SNPs were not." (PMID 21029472, 2010). "Most recently it has been shown that plasma-derived microparticles (MPs) from malaria-infected mice can induce TNF production by macrophages suggesting that MPs may also contribute to the systemic inflammation that is characteristic of malaria infection." (PMID 20126448, 2010). "One speculates that high levels of the Th2 cytokines (IL-10) during helminth infection counteract the Th1 cytokines (TNF) induced by malaria to prevent the development of severe anemia." (PMID 20574512, 2010). "A further consideration in future studies should be the effects of other genes with important immunological functions in the region surrounding the TNF locus that could contribute to the development of severe malaria." (PMID 21029472, 2010). "Plasma concentrations of total TNF, as well as the sTNFRII∶TNF ratio, were significantly increased in association with disease severity, suggesting that a greater proportion of total TNF is bound by sTNFRII in severe malaria, potentially reducing TNF bioavailability." (PMID 19390618, 2009). "TNF-α expression showed a trend to increase in infected placentas and the balance of the immuno-modulatory molecules IL-12 and IL-10 expression denoted an anti-inflammatory response in the course of the placenta malaria pathogenesis." (PMID 19461965, 2009). "Significantly higher TNF levels were observed in patients with severe malaria." (PMID 18194515, 2008). "In particular, the severity of malaria has been correlated with high systemic levels of TNF." (PMID 18369465, 2008). "It seems that TNF-α which is activated following the release of malaria antigens after schizont rupture, may activate production of IP-10 in brain capillaries and astrocytes." (PMID 18489763, 2008). "To perform the molecular characterization of TNF-inducing factors from Plasmodium, we used a model system in which we measured the release of TNF from cultures of murine in vitro-differentiated dendritic cells (DCs) in response to erythrocytes infected with the rodent malaria parasite P. yoelii." (PMID 18369465, 2008). "Whether IFNγ, TNFα and IL-10 regulate the self-reactive antibody response during malaria, as is the case for primary biliary cirrhosis, remains to be shown." (PMID 17460756, 2007). "Severe malaria is associated with sequestration of Plasmodium falciparum-infected red blood cells (PRBC) in the microvasculature and elevation of intercellular adhesion molecule-1 (ICAM-1) and TNF." (PMID 17383656, 2007). "Interestingly the characteristics of this fraction were congruent with those of the malaria parasite-derived TNF-inducing GPI moieties studied by other workers." (PMID 17517147, 2007).